LEP (leptin)
Diseases named in the same sentence as LEP in open-access papers (continued):
Sharing a sentence is not in itself a finding about the gene and the disease.
morbid obesity (64 papers, 2007 to 2025). An excess of body weight, normally defined as an individual with a body mass index greater than 35 or a body weight greater than one hundred percent of ideal body weight. "We present the case of a patient with morbid obesity due to a single mutation in the LEP gene and approximately four years of treatment with metreleptin as a substitute therapy." (PMID 41013830, 2025). "Mutation in the leptin gene causes a marked decrease in leptin levels, leading to intense hyperphagia and associated morbid obesity." (PMID 41013830, 2025). "In a case-control study, SNPs of exons in LEP were found to be rare but associated with morbid obesity and altered levels of serum leptin in Kerala, India." (PMID 37207234, 2023). "Ironically, leptin insufficiency is the root cause of morbid obesity, and people with this condition have elevated leptin levels." (PMID 37860004, 2023). "A novel synonymous mutation Thr5Thr of exon 2 of LEP was identified in heterozygous form in one subject with morbid obesity with hyperleptinemia." (PMID 36619235, 2022). "A novel synonymous mutation Thr5Thr (rs142904532) in exon 2 of LEP was found to be associated with morbid obesity." (PMID 36619235, 2022). "This mutation in heterozygous form was associated with morbid obesity with very high serum leptin level." (PMID 36619235, 2022). "Mutations in the exons of leptin gene were found to be rare but associated with morbid obesity and altered levels of serum leptin." (PMID 36619235, 2022). "In our study, rare SNPs of mutations Thr5Thr, Phe17Leu, and Lys36Arg were detected and were found to be associated with low leptin levels and morbid obesity." (PMID 36619235, 2022). "SNPs of exons in LEP were found to be rare but associated with morbid obesity and altered levels of serum leptin in the study population in Kerala, India." (PMID 36619235, 2022). "In mammals, leptin (ob/ob) and leptin receptor (db/db) deficiencies lead to excessive hyperphagia, morbid obesity, and a diabetic phenotype." (PMID 35454105, 2022). "LEP rs2167270 G>A polymorphism, which involves the untranslated 5-prime region of the gene and results in a single A-to-G transition in the 26th nucleotide, is associated with low leptin levels and morbid obesity." (PMID 32986381, 2020). "It has also been found that mutations of the LEPR gene results in leptin insensitivity, hyperphagia, morbid obesity, as well as metabolic and endocrine abnormalities." (PMID 26365669, 2015). "In ob/ob mice, displaying a phenotype similar to that of human obesity, a point mutation of the ob gene encoding for leptin, accounts for hyperphagia, morbid obesity, and sterility." (PMID 24895638, 2014). "Leptin is a regulator of energy balance and leptin deficiency in experimental animals leads to hyperphagia and morbid obesity." (PMID 25333960, 2014). "Altogether, it appears that the emergence of morbid obesity in the OLETF strain is either caused or accompanied by the disruption of the leptin system, which worsens their innate hyperphagic phenotype." (PMID 23544111, 2013). "In humans, leptin plays a crucial role in regulation of body weight, as demonstrated by morbid obesity in patients with congenital mutations in either leptin or the leptin receptor gene." (PMID 21995317, 2011). "Homozygous frameshift (ΔG133) and missense (R105W) mutations of LEPTIN gene have been identified in patients with morbid obesity." (PMID 21151569, 2010). "It is known that humans leptin-deficient present severe hyperphagia and morbid obesity and that the replacement of methyl-recombinant human leptin (metreleptin) in these patients leads to an almost complete reversal of this phenotype." (PMID 27713360, 2010). "At high levels, leptin inhibits food intake through the melanocortin receptor system, and at low levels, it promotes food intake through neuropeptide Y. Mutations in the LEPR gene result in leptin insensitivity, hyperphagia, morbid obesity, and metabolic and endocrine abnormalities." (PMID 31480192, 2020).
morbid obesity (continued). "The importance of leptin in the control of systemic energy homeostasis is demonstrated by clinical observations in people with genetic loss of leptin, which develop hyperphagia and morbid obesity in early childhood that can be reversed by leptin replacement therapy." (PMID 30283080, 2019). "Congenital leptin deficiency leads to uncontrolled appetite and morbid obesity in humans." (PMID 29910808, 2018). "Although leptin can be secreted into the blood by a wide variety of tissues, in the case of morbid obesity, the most important tissues are the stomach and adipose tissue." (PMID 39062791, 2024). "The inability of ob/ob mice to synthesize leptin leads the organism to exhibit a state of morbid obesity and hyperphagia." (PMID 37860765, 2023). "Adipose hormone leptin critically regulates body weight and metabolism, and disruption of leptin/leptin receptor (LepR) signaling results in morbid obesity and severe metabolic disease." (PMID 32251290, 2020). "The second variant, which is R105W, was reported in a study conducted on an obese patient who presented a reduced serum Leptin concentration and related to morbid obesity." (PMID 31871931, 2019). "The goal of this study was to explore the potential role of leptin on perioperative respiratory function, assessed by gas exchange analysis, in patients with morbid obesity undergoing bariatric surgery." (PMID 29975721, 2018). "Several studies have reported that mutations in the genes encoding leptin (LEP) and its receptor (LEPR) have been associated with hyperphagia and morbid obesity." (PMID 28428959, 2017). "A number of studies have revealed that increased plasma leptin concentration is correlated with higher blood pressure, higher cholesterol level, and morbid obesity." (PMID 26413164, 2015). "Additionally, morbid obesity can impair lymphatic clearance via adipose‐tissue-related cytokines (e.g., leptin) and microvascular dysfunction, prolonging steroid retention and tissue toxicity." (PMID 41018370, 2025). "Therefore, investigating therapeutic strategies targeting these inflammatory mediators holds promise for improving the prognosis of patients with CP and reducing complications, particularly leptin resistance and subsequent morbid obesity." (PMID 38965454, 2024). "Furthermore leptin promotes the differentiation of granulocytes, inducing leucocytosis, the well-known process which accompain the low-grade of inflammation of morbid obesity." (PMID 38904913, 2024). "In addition, hypothalamic resistance to circulating peptides, such as leptin resistance, was also thought to contribute to the development of morbid obesity." (PMID 37509115, 2023). "Taken together, we suggest a model in which leptin depletion via rs10487505 enhances weight gain in normal-weight individuals but prevents leptin resistance and further the dysregulation of appetite and satiety in patients with morbid obesity." (PMID 36833305, 2023). "In contrast, in patients with morbid obesity, leptin depletion might act as a preventative factor for the development of leptin resistance, therefore preserving the physiological regulation of satiety and appetite to some extent." (PMID 36833305, 2023). "Therefore, therapeutic strategies based on leptin resistance and the leptin/leptin receptors axis offer options for solving morbid obesity in patients with CP in the future." (PMID 37509115, 2023). "Among these substances, leptin seems to have an integral role in morbid obesity." (PMID 29975721, 2018). "While mouse models with deficient IL-6 signaling show an ameliorated but not absent Diethylnitrosamine (DEN)-induced HCC development, the morbid obesity in mice with mutant leptin signaling complicates the dissection of hepatic leptin receptor (LEPR) and IL-6 signaling in HCC development." (PMID 30224299, 2018). "While leptin deficiency or dysfunction leads to morbid obesity, obese subjects are characterized paradoxically by hyperleptinemia indicating lack of response to leptin." (PMID 29910808, 2018).
morbid obesity (continued). "Thus, unlike neurosensory hearing loss or anosmia, metabolic defects are not typically considered as primary events in CHH, apart from syndromic CHH caused by LEP, LEPR, or PCSK1 mutations resulting in both GnRH deficiency and morbid obesity." (PMID 28754744, 2017). "The lack of leptin action causes a disruption in energy balance with hyperphagia and decreased energy expenditure, leading to morbid obesity and development of type 2 diabetes." (PMID 21151569, 2010). "However, it remains unclear whether inflammatory mediators secreted by tumor cells contribute to leptin resistance characterized by elevated plasma leptin in patients with CP, consequently leading to morbid obesity." (PMID 38965454, 2024). "Adipokines such as leptin, TNFα and adiponectin have demonstrated cardiovascular activity with circulating leptin levels correlating with LV mass in morbid obesity and may also be responsible in contributing to the beneficial cardiac effects of bariatric surgery." (PMID 38007595, 2024). "Furthermore, no deleterious mutations were found in genes known to cause morbid obesity such as leptin, leptin receptor, melanocortin 4 receptor, POMC, adiponectin and adiponectin receptor." (PMID 23300646, 2012). "In normal-weight individuals, leptin serum concentration fluctuates between 2.65 and 46 ng/mL, whereas in obese subjects, it is possible to find leptin concentrations as high as 100 ng/mL, and even a 150 ng/mL concentration could be reached in cases of morbid obesity." (PMID 36291097, 2022). "A linkage analysis in French families with morbid obesity showed linkage between ISL1 and BMI and leptin." (PMID 32153512, 2020). "The hormone leptin, discovered in 1994, critically regulates body weight and metabolism at central level in the brain, and disruption of leptin/leptin receptor (LEPR) signaling results in morbid obesity and severe metabolic disease." (PMID 32630697, 2020). "Hence, the muscle phenotype of db/db and ob/ob diabetic mice is probably not representative of the human muscle in the common form of adult-onset type 2 diabetes but rather of a rare subset of human morbid obesity due to lack of function of leptin and its receptor." (PMID 34082690, 2021).
pancreatic cancer (62 papers, 2004 to 2025). "In a large study with Mendelian randomization, leptin and its receptor were unrelated to pancreatic cancer risk." (PMID 40940878, 2025). "For instance, elevated leptin levels correlate with breast, and lung cancers, while lower levels of leptin are associated with pancreatic cancer." (PMID 38534454, 2024). "Elevated levels of serum leptin have been unequivocally correlated to an increased risk of developing various tumor forms: testicular, breast, prostate, colon, and pancreatic cancers." (PMID 34356668, 2021). "Clinically, high prediagnostic levels of serum leptin are associated with an increase in the risk of pancreatic cancer (odds ratio = 2.55 (95% CI, 1.23–5.27)." (PMID 31835454, 2019). "Concordantly, we found that a higher score of proinflammatory composite biomarker comprising MCP1, PAI1, and leptin was associated with an increased risk of pancreatic cancer." (PMID 29573228, 2018). "In vitro studies demonstrated growth and metastasis of a murine pancreatic cancer cell line was shown to be increased in genetically obese mice caused by loss of leptin or loss of the long isoform of the leptin receptor." (PMID 25919692, 2015). "The increasing prevalence of PanNENs, the proven connection between leptin, adiponectin, and pancreatic cancer, and the unreported association with PanNENs highlight the importance of achieving a clear understanding of the underlying mechanisms involved in the development of PanNENs." (PMID 37444627, 2023). "Indeed, has been reported, in two different patients’ cohorts, also the role of leptin in increasing pancreatic cancer risk." (PMID 32411709, 2020). "Importantly, increased leptin release and resistance are associated with obesity and a growing body of evidence suggests their involvement in promoting pancreatic cancer progression." (PMID 32659999, 2020). "In fact, leptin signaling is linked to the development of several cancer types, including pancreatic cancer, through different mechanisms including the production of inflammatory factors (IL-1, IL-6, and TNF-α), which have been shown to promote tumor invasion and metastasis." (PMID 32604970, 2020). "Furthermore, lean women with a higher proinflammatory composite biomarker score comprised of MCP1, PAI1, and leptin had an increased risk of pancreatic cancer." (PMID 29573228, 2018). "However, we found that higher leptin concentrations were associated with increased risk of pancreatic cancer in those who were followed up for ≥10 years, but with significantly decreased risk in those who were followed up <10 years." (PMID 29573228, 2018). "High MCP1 (aOR Q4 vs. Q1 = 2.55, 95% CI: 1.41–4.61) and the higher CBS including MCP1, PAI1, and leptin (aORQ4 vs. Q1 = 1.82, 95% CI = 1.04–3.18) were also associated with increased pancreatic cancer risk among women with BMI <25 kg/m2 (P values for interaction <0.05)." (PMID 29573228, 2018). "Nevertheless, we observed a suggestive significant inverse association between leptin and risk of pancreatic cancer among women who were followed up for <10 years, whereas leptin was associated with a significant increased risk of pancreatic cancer among women who were followed up for ≥10 years." (PMID 29573228, 2018). "Because pancreatic cancer patients usually have pathological weight loss or cachexia, the decreased leptin concentrations may be secondary to the loss of body fat mass." (PMID 25948792, 2015). "Here, we examined levels of typical serological factors, such as IL-6, TNF-α, and leptin, and used metabolomics to identify metabolites associated with cachexia in patients with pancreatic cancer and investigate intra-day variations in levels of these metabolites." (PMID 25411961, 2014). "However, association between leptin levels and weight loss was noted in a cohort of lung, and pancreatic cancer patients." (PMID 20920199, 2010).
pancreatic cancer (continued). "Besides adipokines, a leptin‐independent mechanism suppressible by weight loss has been demonstrated in leptin‐deficient obese mice, in which an aberrant expression of the intestinal peptide hormone cholecystokinin in pancreatic beta cells enhances pancreatic cancer growth." (PMID 40129249, 2025). "Similarly, using MPE, Babic and colleagues showed that higher levels of plasma leptin were associated with increased risk of pancreatic cancer in men, whereas in women a single nucleotide variant at the leptin receptor gene (rs10493380) was associated with pancreatic cancer risk." (PMID 30249004, 2018). "In vitro studies further showed that leptin increases the migratory capacity of pancreatic cancer cells." (PMID 40427173, 2025). "Increased insulin and leptin levels have been previously observed in diet-induced obese mice with pancreatic cancer." (PMID 39599705, 2024). "Intraductal papillary mucinous neoplasm (IPMN) dysplastic grade, which can progress to pancreatic cancer, correlates with circulating leptin levels." (PMID 37444627, 2023). "Differentiation of cancer was also analyzed in terms of adiponectin and leptin concentrations in pancreatic cancer." (PMID 37444627, 2023). "Previous studies have indicated that leptin up-regulates Notch signaling in breast and pancreatic cancer cells." (PMID 38152619, 2023). "Several studies have shown a link between leptin, adiponectin, and gastrointestinal cancers together with pancreatic cancer." (PMID 37444627, 2023). "Rapamycin also significantly reduces pancreatic tumor growth and mTOR-related signaling and can normalize elevated serum leptin levels through the PI3K/mTOR signaling pathway." (PMID 37444627, 2023). "Adiponectin can effectively inhibit proliferation and also induce apoptosis in pancreatic cancer cell lines indirectly by antagonizing leptin-induced signal transducer and activator of transcription 3 (STAT3) activation." (PMID 37444627, 2023). "Another study by Yuan shows significantly decreased circulating leptin levels in pancreatic cancer patients compared with non-pancreatic cancer individuals." (PMID 37190276, 2023). "We have previously shown that adiponectin inhibits pancreatic cancer by antagonizing leptin-induced STAT3 activation." (PMID 35121743, 2022). "Leptin overexpression promotes human pancreatic cancer xenograft growth and lymph node metastasis in mice, inducing the progression throughout the cell cycle and the expression of pancreatic cancer stem cell (CSC) markers (CD24+, CD44+, ESA+, ALDH+)." (PMID 33670492, 2021). "The leptin antagonist, IONP-LPrA2, was also used to reduce leptin-induced effects in pancreatic cancer (PC) cells." (PMID 34356668, 2021). "In a pooled, nested case-control study, increased leptin concentrations correlated with pancreatic cancer, but only after a long follow-up of 10 or more years." (PMID 34680216, 2021). "Leptin induces cell migration, invasion, and metastasis in an orthotopic model of pancreatic cancer, and the simultaneous increase in the expression of leptin receptor and MMP13 also shows a positive association with the TNM stage." (PMID 33804101, 2021). "Leptin can specifically bind to the leptin receptor (ObR) expressed in pancreatic cancer and promote the migration and invasion of pancreatic cancer cells but does not affect the proliferation ability of pancreatic cancer cells." (PMID 34485124, 2021). "High leptin expression has also been found in pancreatic cancer, renal cell carcinoma, prostate cancer, ovarian cancer, bladder cancer, or gallbladder cancer." (PMID 34202969, 2021). "LEP is also involved in the regulation of pancreatic cancer cell proliferation, energy metabolism, and chemotherapy resistance." (PMID 33169793, 2020). "Conversely, AdipoRon, a small molecule agonist for both adiponectin receptors, induced PC cell apoptosis and reduced pancreatic tumor growth, presumably via downregulation of the leptin/STAT3 signaling." (PMID 32659999, 2020).